GAS5 (growth arrest specific 5)
Diseases named in the same sentence as GAS5 in open-access papers (continued):
Sharing a sentence is not in itself a finding about the gene and the disease.
lung adenocarcinoma (continued). "Induced expression of GAS5 decreases the IGF-1R activity and overcomes gefitinib-resistance in lung adenocarcinoma." (PMID 31847392, 2019). "The aim of the current study was to evaluate the combined effect of the single nucleotide polymorphism (SNP) in long non-coding RNA growth arrest-specific 5 (GAS5) and the phenotypes of epidermal growth factor receptor (EGFR) on the clinicopathological characteristics of lung adenocarcinoma." (PMID 36011604, 2022). "One study revealed that GAS5 was significantly downregulated in lung adenocarcinoma tissues compared with paired adjacent nontumorous tissue samples." (PMID 30853980, 2019). "Our results showed that GAS5 was significantly downregulated in lung adenocarcinoma tissues compared with the paired adjacent non-tumorous tissue samples." (PMID 25925741, 2015). "We found that the GAS5 expression levels were significantly downregulated in lung adenocarcinoma lesions compared with the adjacent noncancerous tissues, which was consistent with previous findings in other cancer types." (PMID 25925741, 2015). "In the subgroup analyses of EGFR wild type, the GAS5 SNP rs145204276 Ins/Del + Del/Del are related the tumor stage and distal metastases of lung adenocarcinoma in the non-smoker population and enhance the lymph node invasion of lung adenocarcinoma in the ever-smoker group." (PMID 36011604, 2022). "Moreover, the GAS5 SNP rs55829688 TC+CC did not alter all the clinical manifestations of lung adenocarcinoma with all types of the EGFR genotype." (PMID 36011604, 2022). "Our results suggest that GAS5 in combination with gefitinib inhibited EGFR activity and the phosphorylation of its downstream pathway components, which is important to overcome resistance, and, finally, restored the sensitivity of lung adenocarcinoma cell lines to the EGFR-TKIs." (PMID 25925741, 2015). "However, the biological role of GAS5 and its function in EGFR-TKI-resistant lung adenocarcinoma remain largely unknown." (PMID 25925741, 2015). "To screen for the expression of GAS5 in the NSCLC cell lines, we used qRT-PCR analysis to assess GAS5 expression in the A549 (K-RAS mutant, EGFR wild-type), H1299 (EGFR wild-type, N-RAS), H1975 (T790M EGFR mutant), and HCC827 (EGFR mutant) lung adenocarcinoma cell lines." (PMID 25925741, 2015).
thyroid cancer (14 papers, 2018 to 2025). "The overexpression of GAS5 enhanced sensitivity to iodine 131 and inhibited the growth of thyroid cancer cells, while the upregulation of miR-362-5p had the opposite effect." (PMID 40463874, 2025). "This study showed that GAS5, as a ceRNA, acts on miR-222-3p in thyroid cancer, leading to activation of the PTEN/AKT pathway and exerting an anti-cancer effect." (PMID 32596158, 2020). "In this study, the expression of lncRNA GAS5 showed significant association with TNM staging, lymph node metastasis, and the several cancer foci of thyroid cancer." (PMID 32760219, 2020). "Moreover, the lncRNA GAS5 was shown to enhance radiosensitivity through miR-362-5p/SMG1 axis in thyroid cancer." (PMID 35600868, 2022). "Besides, another study indicated that the expression level of lncRNA Growth Arrest-specific Transcript 5 (GAS5) was negatively related to the LNM of thyroid carcinoma." (PMID 29368602, 2018). "The upregulation of miR-362-5p counteracted the effects of GAS5, and the overexpression of SMG1 negated the impact of miR-362-5p upregulation on iodine 131-resistant thyroid cancer cells." (PMID 40463874, 2025). "Sedaghati summarized the dysregulated and functional LncRNAs in thyroid cancer, including 28 upregulated LncRNAs, such as ANRIL, BANCR, H19, HOTAIR, MALAT1, and NEAT1, and 22 downregulated LncRNAs, including GAS5, NAMA, PTCSC2, and PTCSC3." (PMID 37874339, 2024). "Low GAS5 expression is related to TNM staging, lymph node metastasis, multiple cancer foci, and poor prognosis in patients with thyroid cancer." (PMID 32596158, 2020). "Therefore, GAS5 may be correlated with diagnosis and prognosis of thyroid cancer." (PMID 32760219, 2020).
triple-negative breast carcinoma (14 papers, 2015 to 2025). An invasive breast carcinoma which is negative for expression of estrogen receptor (ER), progesterone receptor (PR), and human epidermal growth factor receptor 2 (HER2). "For incidence, the cell proliferation is inhibited and the apoptosis is induced by LncRNA GAS5 through regulating the PI3K/Akt/mTOR signaling pathway of triple negative breast cancer." (PMID 39651612, 2024). "In triple-negative breast cancer cells, lncRNA GAS5 promotes cancer cell apoptosis by targeting miR-378a-5p, and the targeting relationship of miR-378a-5p and cyclin G2 has been confirmed by luciferase reporter assay in BeWo cells." (PMID 37025425, 2023). "For example, the recent study has found long non-coding RNA GAS5 (lncRNA GAS5) overexpression promotes cell apoptosis via regulating miR-378a-5p/SUFU axis in triple-negative breast cancer cells." (PMID 34587874, 2021). "CpG methylation of the promoter region of the GAS5 gene was reportedly increased in triple-negative breast cancer (TNBC) tissues and TNBC cell lines, while the expression of GAS5 was suppressed in these tumor cells." (PMID 34202777, 2021). "Furthermore, the aberrant promoter methylation is involved in the regulation of GAS5 gene expression in triple-negative breast cancer and some other carcinomas." (PMID 34202777, 2021). "The results of this study highlight the potential role of epigenetic regulation of ADIPOQ, GAS5, GATA4, and YAP1 in the molecular pathology of triple-negative breast cancer." (PMID 41226688, 2025). "In addition, GAS5 also sponges miR-221-3p, which downregulates DKK2, an essential inhibitor of the Wnt/β-catenin pathway, specifically in triple-negative breast cancer (TNBC)." (PMID 39958058, 2025). "Moreover, lncRNA GAS5 was downregulated in triple-negative breast cancer (TNBC) and elevation of lncRNA GAS5 has been verified to inhibit the proliferation of TNBC cells and accelerate apoptosis." (PMID 32308561, 2020).
asthma (13 papers, 2019 to 2025). "GAS5 is downregulated in childhood pneumonia, acute lung injury, and asthma, and its overexpression can cause the inhibition of inflammation and epithelial cell apoptosis." (PMID 38212314, 2024). "Notably, H19, MEG3, GAS5, miR-26a-1-3p, and miR-376a-3p have been implicated in both asthma and obesity, suggesting their role in linking metabolic dysfunction with airway pathology." (PMID 41156032, 2025). "In this context, another lncRNA, GAS5, has been identified as a potential biomarker of asthma, showing higher expression in asthmatic patients compared to healthy controls." (PMID 41156032, 2025). "In acute lung injury, asthma, childhood pneumonia, and other diseases, GAS5 can affect the pyroptosis of bronchial epithelial cells, inhibit inflammatory responses and apoptosis, and promote the proliferation of airway smooth muscle cells." (PMID 38212314, 2024). "Expression levels of OIP5-AS1, MZF1-AS1, HOTAIRM1, and GAS5 in whole blood from the healthy adolescent population, obese adolescents, allergic asthma adolescents, and obesity-related asthma adolescents are differently expressed." (PMID 37047453, 2023). "After that, we tested the discriminative value of these lncRNAs through the area under the curve ROC analysis and interestingly found that HOTAIRM1 and GAS5 can help discriminate between any asthma phenotype of healthy and obese patients." (PMID 37047453, 2023). "HOTAIRM1 and GAS5 showed similar expression behavior, higher expression levels were observed in both asthmatic phenotypes, allergic asthma, and obesity-related asthma compared with their counterparts, healthy and obese adolescents, respectively." (PMID 37047453, 2023). "Mechanistically, in the luciferase reporter assay, cotransfection and verification of cell proliferation, PDGF-BB was proposed to promote ASMCs proliferation via GAS5/miR-10a/BDNF regulatory axis in asthma." (PMID 33013382, 2020). "GAS5 knockdown has the capability to attenuate ASMCs proliferation in asthma, which can be a target to modulate airway remodeling." (PMID 33013382, 2020). "Glucocorticoid is an important treatment for asthma, while lncRNA GAS5 is a decoy for glucocorticoid receptor." (PMID 32929606, 2020). "But, the fact that in a later study the expression of GAS5 was found to be higher in asthmatics, and knock-down of GAS5 significantly decreased airway hyperresponsiveness in asthmatic rats, together with our results indicate their possible roles in asthma." (PMID 33168013, 2020). "For glucocorticoid-resistant asthma, lncRNA GAS5 was found to function as a glucocorticoid receptor." (PMID 30941157, 2019). "Furthermore, it was shown that, in the treatment of steroid-resistant asthma, lncRNA GAS5 acts as a glucocorticoid receptor, and pro-inflammatory mediators increase the amount of GAS5 both in airway smooth muscle cells and in the airway epithelium." (PMID 40722500, 2025). "Thus, further experiments with the OIP5/GAS5 signature should be designed to test its potential ability to predict the development of asthma in the context of obesity-related asthma." (PMID 37047453, 2023). "There is a significant knowledge gap where more molecular biomarkers are needed; we think that OIP-5AS1 and lncRNA GAS5 could help in the future to understand better molecular mechanisms involved in asthma and obesity pathophysiology." (PMID 37047453, 2023). "Furthermore, the expression levels of OIP5-AS1 and GAS5 may help to discriminate between obesity alone and obesity-related asthma." (PMID 37047453, 2023). "Furthermore, our results suggest that OIP5-AS1 and lncRNA GAS5 could be a cornerstone that helps to explain how obesity is directly related to asthma." (PMID 37047453, 2023). "Furthermore, OIP5-AS1 and GAS5 could help to differentiate obesity alone from obesity-related asthma, and OIP5-AS1 and MZF1-AS1 may help to discriminate between asthma endotypes." (PMID 37047453, 2023).
asthma (continued). "Thus, targeting the GAS5/miR-10a/BDNF regulatory axis could significantly decrease airway hyperresponsiveness and reduce the progression of asthma." (PMID 39941145, 2025). "However, our results suggest that HOTAIRM1, GAS5, MZF1-AS1, and OIP5-AS1 could be potential biomarkers to help clinicians accurately stratify different asthma phenotypes, which would have an indirect impact on the early diagnosis and quality of life of asthmatic patients." (PMID 37047453, 2023). "First, we found higher levels of lncRNAs: HOTAIRM1, GAS5, MZF1-AS1, and OIP5-AS1 in the allergic asthmatic and obesity-related asthma patients compared with their counterparts’ healthy adolescents and obesity without asthma adolescents, respectively." (PMID 37047453, 2023).
osteoarthritis (13 papers, 2019 to 2023). A noninflammatory degenerative joint disease occurring chiefly in older persons, characterized by degeneration of the articular cartilage, hypertrophy of bone at the margins and changes in the synovial membrane. "The association between lncRNA GAS5 and miR-21 has been reported in many physiological and pathological processes, including cardiac fibrosis, osteoarthritis, and cancer." (PMID 34526907, 2021). "Moreover, GAS5 has also been implicated as a pathogenic lncRNA in inflammatory conditions, including osteoarthritis." (PMID 35340210, 2022). "GAS5, as a negative regulator of miR-21, mediates the survival of chondrocytes and participates in the occurrence of osteoarthritis." (PMID 37821982, 2023). "LncRNA PVT1 and GAS5 (growth arrest specific 5) regulated each other to govern chondrocyte apoptosis in osteoarthritis." (PMID 37779916, 2023). "Long non-coding RNA (lncRNA) plasmacytoma variant translocation 1 (PVT1) and growth arrest specific 5 (GAS5) have opposite functions in the apoptosis of chondrocytes, which are involved in the pathogenesis of osteoarthritis (OA)." (PMID 35706414, 2022). "The ectopic expression of GAS5 in human osteoarthritis chondrocytes elevates MMP-3 expression and reduces the contents of Collagen II and aggrecan." (PMID 34413821, 2021). "For example, GAS5 contributes to the pathogenesis of osteoarthritis by acting as a negative regulator of miR-21 and thereby regulating chondrocytes survival." (PMID 33195407, 2020). "Previous studies have suggested a link between GAS5 and miR-21 in the pathogenesis of cancer 15, osteoarthritis 23, and cardiac fibrosis 21 and shown that miR-21 is a direct target of GAS5." (PMID 31534503, 2019). "Interestingly, growth-arrest-specific 5 (GAS5), a long ncRNA, plays a pivotal role in controlling miR-21 during the progression of osteoarthritis." (PMID 37685951, 2023). "Moreover, studies have reported that GAS5 acts as a “miRNA sponge” to regulate miR-21 expression in many other diseases, including cancer 15, osteoarthritis 23, and cardiac fibrosis." (PMID 31534503, 2019). "Besides, a negative correlation of GAS‐5 with IL‐10 was also observed in osteoarthritis." (PMID 34936242, 2022).
leukemia (12 papers, 2015 to 2026). A malignant (clonal) hematologic disorder, involving hematopoietic stem cells and characterized by the presence of primitive or atypical myeloid or lymphoid cells in the bone marrow and the blood. "Strikingly, high plasma levels of LINC01268 (p = 0.0018), GAS5 (p = 0.0008) or MALAT1 (p = 0.0348) are also associated with a poor overall-survival while high levels of LINC01268 correlate with a shorter leukemia-free-survival." (PMID 34638230, 2021). "Although the role of GAS5 deregulation has been studied in different types of solid cancers, its impact on the development and prognosis in leukemias, especially in AML, has rarely been investigated." (PMID 35054253, 2021). "In the case of leukemia, there is one report suggesting the interaction of GAS5 with miR-222, since their expression is negatively correlated." (PMID 33076450, 2020). "The evaluation of lncRNAs expression in plasma samples from leukemia and multiple myeloma showed that TUG1, MALAT1, HOTAIR and GAS5 are more highly expressed in leukemia than in the control samples, and only lincRNA-p21 is upregulated in multiple myeloma." (PMID 25338714, 2015). "GAS5 can increase the resistance of mammalian targeted rapamycin (mTOR) antagonists in leukemia." (PMID 37993867, 2023). "GAS5 has been discovered to perform an adversarial role in leukemia carcinogenesis control." (PMID 35736636, 2022). "GAS5 may also function in leukemia cell drug responsiveness through other additional mechanisms not dependent on GR." (PMID 33799946, 2021). "Thus, in steroid-sensitive cancer cells, such as leukemia cells, the GR binding motif is responsible for GAS5 effects on cell growth." (PMID 33799946, 2021). "GAS5 is of great importance in other types of leukemia, like in certain types of B-ALL characterized by hyperdiploidy or the presence of TCF3/PBX1 rearrangement, but its significance is related to the treatment of ALL, that is, to the administration of glucocorticoids in therapy protocols." (PMID 35054253, 2021). "In leukemia, higher GAS5 expression was shown to correlate with poor overall survival." (PMID 33799946, 2021). "Furthermore, GAS5 may mediate regulatory interactions of miRNAs and target mRNAs involved in drug responses, including miR-222 in leukemia cells." (PMID 33799946, 2021). "In this context, lncRNAs such as GAS5, MEG3, CCND1, MORT, and LincRNA-p21 are downregulated in breast, lung, prostate, and renal cancers, as well as in leukaemia and lymphomas." (PMID 41597397, 2026).
osteoporosis (12 papers, 2020 to 2023). A condition of reduced bone mass, with decreased cortical thickness and a decrease in the number and size of the trabeculae of cancellous bone (but normal chemical composition), resulting in increased fracture incidence. "The systemic supplement of Gas5-overexpressing adenoviruses significantly ameliorated bone loss in an osteoporosis mouse model." (PMID 33006314, 2020). "Bone loss in the osteoporosis mouse model was improved by systemic transfection of Gas5-overexpressing adenoviruses." (PMID 33006314, 2020). "Systemic transfection (tail vein injection) of Gas5-overexpressing adenoviruses alleviated bone loss in osteoporosis." (PMID 33006314, 2020). "Bone loss was found to be alleviated in an osteoporosis mouse model after systemic application with Gas5-overexpressing adenoviruses." (PMID 33006314, 2020). "However, it is still unclear whether GAS5 affects osteoblast differentiation and whether GAS5 is associated with osteoporosis." (PMID 33006314, 2020). "In vivo, Gas5 genetic deletion (Gas5+/−) in mice decreased bone mass and impaired bone repair, leading to osteoporosis." (PMID 37370745, 2023). "Researchers found that GAS5 levels were decreased in BMSCs and bone tissues of osteoporosis patients." (PMID 36553535, 2022). "Nonetheless, in line with our results, circulating levels of GAS5 were increased in plasma of patients affected by some tumors, like mesothelioma, and other pathological conditions, like osteoporosis." (PMID 34638230, 2021). "Overall, although many researchers are currently evaluating the mechanisms through which GAS5 mediates osteoporosis, information is still limited, and more robust studies are needed to confirm these findings." (PMID 35155450, 2021). "Given the crucial role of BMSCs in osteoporosis, we explored the variation tendency of GAS5 expression during osteoblast differentiation of BMSCs." (PMID 33006314, 2020). "(B) H and E staining and Bglap immunohistochemical staining of the terminal femur of the control mice (n = 6), osteoporosis mouse model (n = 6) or Gas5-overexpressing adenovirus-treated mice (n = 6)." (PMID 33006314, 2020). "(C, D, E, F, G) BV/TV, BA/BV, trabecular thickness, trabecular number, and trabecular spacing analysis for the control mice (n = 6), osteoporosis mouse model (n = 6) or Gas5-overexpressing adenovirus-treated group (n = 6)." (PMID 33006314, 2020). "To investigate the therapeutic effects of Gas5 on osteoporosis, we induced osteoporosis in mice with dexamethasone (DXMS) and injected Gas5-overexpressing adenoviruses or negative control." (PMID 33006314, 2020). "Herein, in our research, we found that as a protective target, GAS5 decreases in both bone tissue and BMSCs, a major origin of osteoblast, of patients with osteoporosis." (PMID 33006314, 2020). "(B) qRT-PCR analysis of GAS5 isolated from cancellous bone between eight patients with postmenopausal osteoporosis and eight patients with hip dysplasia (n = 8)." (PMID 33006314, 2020). "(A) Micro-CT analysis of the control mice (n = 6), osteoporosis mouse model (n = 6) or Gas5-overexpressing adenovirus-treated mice (n = 6)." (PMID 33006314, 2020). "Our current research found that GAS5 was decreased in the bones and BMSCs, a major origin of osteoblast, of osteoporosis patients." (PMID 33006314, 2020). "In our current research, we found that the level of GAS5 was decreased in both the bones and BMSCs of osteoporosis patients." (PMID 33006314, 2020). "To clarify the possible role of Gas5 in osteoporosis treatment, we supplemented Gas5-overexpressing adenoviruses in an osteoporosis mouse model based on the preceding results." (PMID 33006314, 2020). "(C) GAS5 mRNA expression level in BMSCs isolated from hip dysplasia and osteoporosis patients (n = 8)." (PMID 33006314, 2020). "In another study, GAS5 was shown to be differentially expressed in patients with osteoporosis." (PMID 35155450, 2021).